FOLH1B (folate hydrolase 1B (pseudogene) )
Gene: Long non-coding RNA gene on chromosome 11 (89,659,297 to 89,698,722, forward strand). Ensembl gene ENSG00000290503.
Diseases named in the same sentence as FOLH1B in open-access papers:
FOLH1B is named in the same sentence as 3 diseases in open-access papers, as found by Europe PMC text mining. Sharing a sentence is not in itself a finding about the gene and the disease. The quoted sentences say what the papers report.
prostate carcinoma (2 papers, 2020 to 2021). A carcinoma that arises from epithelial cells of the prostate gland. "Studies suggest FOLH1B may play an important role in the development and progression of prostate cancer." (PMID 34375949, 2021).
psychiatric disorder (1 paper, 2023). A disorder characterized by behavioral and/or psychological abnormalities, often accompanied by physical symptoms. "The gene with the most interactions was, with pAUDIT using PFC expression, FOLH1B, an untranslated pseudogene previously associated with psychiatric disorders and BMI." (PMID 37216417, 2023).
tumor (1 paper, 2020). "Consistently, all the six DEGs (GLS2, ASS1, FOLH1B, AGXT2, CPS1, and GPT2) enriched in “arginine biosynthesis” in our results were significantly downregulated in tumor hepatic tissue from HBV-infected patients compared with adjacent nontumor tissues." (PMID 32775402, 2020).